WTAP (WT1 associated protein)
Description:
Associated component of the WMM complex, a complex that mediates N6-methyladenosine (m6A) methylation of RNAs, a modification that plays a role in the efficiency of mRNA splicing and RNA processing. Required for accumulation of METTL3 and METTL14 to nuclear speckle. Acts as a mRNA splicing regulator. Regulates G2/M cell-cycle transition by binding to the 3' UTR of CCNA2, which enhances its stability. Impairs WT1 DNA-binding ability and inhibits expression of WT1 target genes.
Synonyms: KIAA0105; MGC3925; Mum2
Tractability: PROTAC: ubiquitination databases record sites on it; its protein half-life has been measured.
Gene: Protein-coding gene on chromosome 6 (159,716,432 to 159,756,319, forward strand). Ensembl gene ENSG00000146457.
Subcellular location: Nucleus speckle; Nucleus, nucleoplasm; Cytoplasm
Subcellular location (Human Protein Atlas): Nuclear speckles
Pathways (Reactome):
Metabolism of RNA: Processing of Capped Intron-Containing Pre-mRNA
Gene Ontology:
Molecular function: identical protein binding; protein binding
Biological process: mRNA processing; regulation of alternative mRNA splicing, via spliceosome; mRNA modification
Cellular component: nuclear membrane; nuclear speck; nucleoplasm; nucleus; RNA N6-methyladenosine methyltransferase complex; cytoplasm
Genetic constraint (gnomAD): Loss-of-function variants: 8 observed, 42.13 expected, observed/expected ratio (o/e) 0.19, 90% interval 0.11 to 0.34. The upper end of that interval is the gene's LOEUF score, 0.34, which puts it in group 1 of 6, group 1 being the genes least tolerant of losing a copy. Missense variants: 272 observed, 440.97 expected, observed/expected ratio (o/e) 0.62, 90% interval 0.56 to 0.68. Synonymous variants: 171 observed, 161.95 expected, observed/expected ratio (o/e) 1.06, 90% interval 0.93 to 1.2.
Homologues: Orthologues: chimpanzee WTAP (99% identical), macaque WTAP (99% identical), guinea pig WTAP (97% identical), rat Wtap (96% identical), mouse Wtap (96% identical), rabbit WTAP (94% identical), tropical clawed frog wtap (84% identical), zebrafish wtap (78% identical), Drosophila melanogaster fl(2)d (38% identical).
Diseases named in the same sentence as WTAP in open-access papers:
WTAP is named in the same sentence as 133 diseases in open-access papers, as found by Europe PMC text mining. Sharing a sentence is not in itself a finding about the gene and the disease. The quoted sentences say what the papers report.
hepatocellular carcinoma (33 papers, 2017 to 2026). A malignant tumor that arises from hepatocytes. "Wilms tumour 1‐associated protein (WTAP) as an m6A writer drives hepatocellular carcinoma (HCC) progression and mediates m6A modification of lncRNA DIAPH1‐AS1 to enhance nasopharyngeal carcinoma metastasis." (PMID 39632285, 2024). "Among the 17 m6A regulators, previous studies have reported that high WTAP expression in hepatocellular carcinoma was associated with poor prognosis; hence, WTAP promoted the growth and proliferation of HCC cells both in vitro and in vivo." (PMID 34291082, 2021). "It was also found that WTAP is highly expressed in liver cancer tissue, and the progress of hepatocellular carcinoma (HCC) is related to the phenotype caused by WTAP deficiency." (PMID 33552994, 2020). "Recent studies have increasingly highlighted the role of Wilms Tumor 1-Associated Protein (WTAP) as a key player in human cancers, including hepatocellular carcinoma (HCC) and bladder cancer." (PMID 40271153, 2025). "This pathway drives oncogenic processes, including cell cycle dysregulation and tumor progression, highlighting WTAP as both a potential therapeutic target and a prognostic indicator in hepatocellular carcinoma." (PMID 40986143, 2025). "For instance, WTAP is overexpressed in hepatocellular carcinoma and drives liver cancer development." (PMID 38171932, 2023). "Overexpression of WTAP related to m6A methylation promotes hepatocellular carcinoma progression via the HuR-ETS1-p21/p27 axis." (PMID 37194014, 2023). "Several studies showed that ncRNAs interact with WTAP to influence hepatocellular carcinoma progression." (PMID 36139062, 2022). "Meanwhile, WTAP plays an important role in the progression of hepatocellular carcinoma by affecting the epigenetic modifications of ETS1." (PMID 35592424, 2022). "LINC00839 upregulates WTAP expression and enhances the malignant features of hepatocellular carcinoma by regulating the miR-144-3p/WTAP axis." (PMID 36139062, 2022). "MiR-139-5p negatively upregulates WTAP expression in hepatocellular carcinoma by targeting the 3′-UTR of WTAP." (PMID 36139062, 2022). "WTAP also promotes the progression of hepatocellular carcinoma via the HuR-ETS proto-oncogene 1 (ETS1) axis, and the upregulation of WTAP in ovarian cancer and bladder cancer is associated with poor prognosis." (PMID 35143566, 2022). "WTAP is highly expressed in cells of hepatocellular carcinoma, osteosarcoma tumorigenesis, gastric cancer, and cholangiocarcinoma, where it is correlated with poor survival outcomes." (PMID 34595849, 2021). "Higher expression level of WTAP was also found in hepatocellular carcinoma (HCC) which is correlated with poor prognosis and low patient survival." (PMID 32194861, 2020). "WTAP expression was up-regulated in hepatocellular carcinoma; WTAP-mediated m6A modification led to epigenetic silencing of the tumor suppressor gene ETS1, and promoted the progression of hepatocellular carcinoma by regulating the cell cycle." (PMID 33363011, 2020). "Supporting our results, other studies have revealed that WTAP promotes tumor cell proliferation in hepatocellular carcinoma, and increases the migration and invasion of cholangiocarcinoma cells by upregulating MMP7." (PMID 28212562, 2017). "In addition, WTAP expression also serves as an independent prognostic biomarker for hepatocellular carcinoma, with elevated levels correlating with poor survival outcomes." (PMID 40986143, 2025). "WTAP serves as a potential therapeutic target of hepatocellular carcinoma therapy." (PMID 37194014, 2023). "WTAP is overexpressed in hepatocellular carcinoma and predicts poor prognosis." (PMID 36139062, 2022). "Overexpression of WTAP contributes to aggressive features of numerous cancers such as renal cell carcinoma, acute myeloid leukemia, diffuse large B-cell lymphoma, cholangiocarcinoma, hepatocellular carcinoma and play a role as oncogene." (PMID 35715447, 2022).
hepatocellular carcinoma (continued). "Moreover, WTAP facilitates the progression of hepatocellular carcinoma via m6A‐HuR‐dependent epigenetic silencing of ETS127 and promotes osteosarcoma tumorigenesis by repressing HMBOX1 expression." (PMID 34595849, 2021). "Indeed, WTAP expression has been connected to couples of malignancies, such as ovarian cancer, hepatocellular carcinoma, pancreatic cancer, bladder cancer, diffuse large B-cell lymphoma, renal cell carcinoma, and pancreatic ductal adenocarcinoma." (PMID 34081626, 2021). "MS results showed that NOA1 might be a potential target of WTAP in hepatoma cells." (PMID 39744575, 2025). "The N6-methyladenosine (m6A) methylase WTAP has been identified as a proto-oncogene in multiple cancers, including hepatocellular carcinoma (HCC)." (PMID 40568348, 2025). "WTAP is involved in various pathological and physiological processes, but its function in hepatocellular carcinoma (HCC) remains elusive." (PMID 35480109, 2022). "Inducing ferroptosis, facilitated by m6A modification of ATG5 mRNA mediated by WTAP and YTHDC2, effectively suppresses hepatocellular carcinoma development, highlighting a promising therapeutic approach." (PMID 39315094, 2024). "However, the in vivo role of WTAP in the pathogenesis of hepatocellular carcinoma (HCC) is unknown." (PMID 37777158, 2023). "In hepatocellular carcinoma, LINC00839 upregulates WTAP expression by acting as a ceRNA contending to bind miR-144-3p." (PMID 36139062, 2022). "Further mechanistic studies revealed that liver kinase B1 (LKB1), the upstream kinase of Adenosine 5′-monophosphate activated protein kinas (AMPK), is regulated by WTAP and mediates AMPK phosphorylation in an m6A-dependent manner, thereby promoting hepatocellular carcinoma autophagy." (PMID 36139062, 2022). "Interestingly, data from flow cytometry by Annexin V-FITC/PI and detection of pyroptosis-related marker Gasdermin D (GSDMD) by Western blot demonstrated that, overexpressing or knocking down WTAP will not affect cell apoptosis and pyroptosis in hepatoma cells." (PMID 39744575, 2025). "A recent study on hepatocellular carcinoma (HCC) found that ferroptosis is regulated by the PPARGC1A/BAMBI/ACSL5 axis, with METTL3 and WTAP inhibiting PPARGC1A in an m6A- and YTHDF2-dependent manner." (PMID 40271153, 2025). "As an adaptor, WTAP is overexpressed in many cancers and serves as an oncogenic protein that can down-regulate the c-Myc, HMBOX1, and ETS1 mRNAs in an m6 A-mediated manner, enhancing the proliferation and metastasis of AML, osteosarcoma, and hepatocellular carcinoma (HCC)." (PMID 40483535, 2025).
glioma (26 papers, 2017 to 2026). A benign or malignant brain and spinal cord tumor that arises from glial cells (astrocytes, oligodendrocytes, ependymal cells). "Another central component of the m6A methyltransferase complex is WTAP that has been implicated in various aspects of glioma progression and treatment response." (PMID 38474421, 2024). "Furthermore, WTAP expression is associated with glioma grade and is an independent prognostic factor for shorter survival in patients with glioma." (PMID 36207306, 2022). "Associations between glioma malignancy grade and the expression of m6 A writers (METTL3, METTL14, WTAP, and RBM15), the reader YTHDF, and erasers (ALKBH5 and FTO) are shown." (PMID 40382536, 2025). "WTAP, another important component of the m6A writer, has increased expression in glioma and can predict poor postoperative survival in glioma patients." (PMID 40469294, 2025). "Together with other genes like TRMT6, DNMT1, and DNMT3B, WTAP can predict overall survival in glioma patients and is correlated with poor post-operative outcomes." (PMID 38474421, 2024). "Knockdown and overexpression studies have shown that WTAP can regulate epidermal growth factor receptor, influencing tumorigenicity in glioma." (PMID 38474421, 2024). "The silencing of FLOT1 led to reduced glioma cell proliferation, highlighting the significance of WTAP in glioma biology." (PMID 38474421, 2024). "The expression of WTAP is significantly increased in gliomas, and is positively correlated with age, glioma grades, and adverse prognosis." (PMID 38072944, 2023). "A similar risk signature (ALKBH5, IGF2BP2, IGF2BP3, HNRNPA2B1, YTHDF1, YTHDF2, RBM15, and WTAP) was shown to be prognostic for glioma patients, and the expression of IGF2BP2 and IGF2BP3 was linked to tumour occurrence, development, and progression." (PMID 36831575, 2023). "The expression of WTAP was highest in the WHO IV (GBM) group among glioma samples of three WHO grades and normal brain samples." (PMID 34354698, 2021). "Remarkably, the expression of WTAP increased in gliomas with higher malignancy, such as higher WHO grade, IDH-wildtype, and molecular subgroups with poorer survival, in both tow datasets." (PMID 34246306, 2021). "Our results indicated that WTAP is localized throughout the nucleoplasm and is overexpressed in glioma tissues and GSCs, suggesting that it is an oncogene in glioma and GSCs." (PMID 28212562, 2017). "WTAP is highly expressed in glioma, and its expression is closely correlated with glioma grade." (PMID 40469294, 2025). "In addition, high WTAP expression is correlated with low postoperative survival in patients with glioma and can be used as a prognostic marker." (PMID 37964279, 2023). "To determine whether WTAP participates in the tumor suppression pathway of miR-29a in GSCs, we evaluated WTAP expression in glioma tissues and GSCs." (PMID 28212562, 2017). "An IHC assay on tissue microarray chips (containing the same tissue samples used in the QKI-6 IHC assay) indicated that WTAP is localized throughout the nucleoplasm in glioma cells and is overexpressed in glioma tissues (especially glioblastoma tissues) compared with normal brain tissues." (PMID 28212562, 2017). "As WTAP is a crucial interactor of the methyltransferase complex, so this works suggested that m6A modification related enzymes and m6A methylation processes may play an oncogenic role in glioma." (PMID 32943100, 2020). "Therefore, WTAP may be a novel prognostic marker for glioma." (PMID 36207306, 2022). "In glioma stem-like cells, METTL3 and METTL14 were also shown to suppress cell differentiation, while WTAP and ALKBH5 promote cell proliferation, self-renewal, and tumorigenicity." (PMID 36293529, 2022). "Recently, another study also analyzed the correlation of m6A regulators and prognostic features and found that HNRNPC, WTAP, YTHDF1, and YTHDF2 were significantly upregulated in glioma tumors in patients with good OS." (PMID 34381710, 2021).
glioma (continued). "In malignant gliomas, WTAP can regulate migration and invasion through EGF signaling, and closely related to glioma severity and postoperative survival rate of glioma patients." (PMID 33552994, 2020). "The expression of WTAP was also significantly correlated with the ‘writers’ of METTL14, KIAA1429 and RBM15 in gliomas." (PMID 30810537, 2019). "However, WTAP, RBM15, YTHDF, and ALBKH5 had strong correlations with tumor stage and 1p/19q codeletion in glioma." (PMID 33926554, 2021). "As is visible in the violin plot, the mRNA expression levels of YTHDF2, YTHDF1, METTL3, RBM15 and HNRNPC were up‐regulated in glioma compared to normal tissues, whereas the expression levels of ALKBH5, WTAP, YTHDC2, ZC3H13 and METTL14, especially of FTO, were decreased in glioma." (PMID 32449290, 2020). "Moreover, the expressions of WTAP, RBM15, YTHDF2, YTHDF1 and ALKBH5 were highly correlated with each other, and all of their expressions were negatively correlated with FTO in gliomas." (PMID 30810537, 2019).
breast carcinoma (22 papers, 2020 to 2025). "In fact, the importance of WTAP in tumor biology has already been demonstrated for various tumor entities, including breast cancer and acute myeloid leukemia, where increased WTAP expression was also associated with poorer overall survival." (PMID 40699665, 2025). "It is unclear as to whether Wilms’ tumor 1-associated protein (WTAP) promotes or suppresses breast cancer." (PMID 35046505, 2022). "Upregulated WTAP expression was associated with less lymph node metastasis in breast cancer." (PMID 36171885, 2022). "Our results highlight the discordant expression profiles of WTAP mRNA and protein not only in breast cancer cell lines, but also extended to cancers datasets." (PMID 38862471, 2024). "This immunohistochemistry analysis explored levels of WTAP expression in 347 cases of breast cancer and analyzed the relationship between WTAP expression and the clinicopathological characteristics and prognosis of breast cancer patients." (PMID 35046505, 2022). "Research on the expression of WTAP in breast cancer tissue and its clinical significance is only available from individual case reports, and contrasting findings have been reported from analyses of the expression and function of WTAP11,12." (PMID 35046505, 2022). "Mechanistically, WTAP promotes the stability of lncRNA DLGAP1-AS1 in breast cancer through m6A modifications." (PMID 36139062, 2022). "This study performed an immunohistochemistry (IHC) analysis of WTAP expression in breast cancer tissue samples obtained from 347 Chinese Han women, to clarify the expression of WTAP in breast cancer and its clinicopathological and prognostic significance." (PMID 35046505, 2022). "We suggest that WTAP expression is upregulated in breast cancer and appears to both promote tumor growth and inhibit lymph node metastasis." (PMID 35046505, 2022). "On the contrary, another study reported that not only METTL3 but also other members of the writer complex such as METTL14 and WTAP are downregulated in breast cancer, suggesting that lower levels of m6A may contribute to breast tumorigenesis." (PMID 36725888, 2023). "The expression of WTAP varied in different in breast cancer studies." (PMID 35721510, 2022). "However, further exploration is required to understand the lncRNA DLGAP1-AS1/miR-299-3p/WTAP regulatory axis in breast cancer." (PMID 36139062, 2022). "However, scant research is available regarding WTAP expression and function in breast cancer, with only two published reports." (PMID 35046505, 2022). "Interestingly, WTAP promotes the stability of lncRNA DLGAP1-AS1 through m6A modification, and lncRNA DLGAP1-AS1 upregulates WTAP expression in breast cancer through 3′-UTR binding to miR-299-3p." (PMID 36139062, 2022). "Moreover, we noticed that protein expression of WTAP was elevated in ovarian cancer and others, including breast cancer, colon cancer, clear cell renal cell carcinoma, and uterine corpus endometrial carcinoma compared with corresponding normal tissues." (PMID 32998774, 2020). "WTAP is a conserved nuclear protein that shows decreased expression in breast cancer." (PMID 32742465, 2020). "Other subunits of METTL3 complex, namely WTAP, RBM15, KIAA1429 (also known as Virilizer homolog or VIRMA), and METTL14, displayed moderate-to-strong staining intensities in both normal and breast cancer tissues." (PMID 36289222, 2022). "Low expression of METTL3, METTL14, WTAP and FTO was shown to correlate with relapse-free survival in breast cancer." (PMID 35721510, 2022). "Among them, the expression of RBM15, VIRMA, HNRNPA2B1, and YTHDF1/2/3 were significantly upregulated, but METTL3, METTL14, METTL16, WTAP, FTO, YTHDC1, and EIF3A had lower expression in breast cancer compared to normal samples." (PMID 34804948, 2021).
breast carcinoma (continued). "In this study, by analyzing the prognostic role of m6A modulators (METTL3, METTL14, WTAP, FTO, and ALKBH5) in breast cancer using on-line databases, we found that only METTL3 played an important role in TNBC metastasis." (PMID 32766145, 2020). "Aberrant expression of m6A regulators, including METTL3, METTL14, WTAP, ALKBH5, and FTO, has been identified in breast cancer, as well as their potential prognostic values." (PMID 33585234, 2020). "In GSE70905, YTHDC1 (p < 0.05), IGFBP1 (p < 0.001), ALKBH5 (p < 0.001), WTAP (p < 0.001), YTHDF3 (p < 0.001) and HNRNPA2B1 (p < 0.001) were down-regulated in breast cancer to the adjacent." (PMID 33362863, 2020). "No increases in METTL3, METTL14 and WTAP protein levels were detected in VIRMA FL-transduced HS578T cells that already express high levels of endogenous full-length VIRMA or in breast cancer cells overexpressing VIRMA N-term compared to control cells." (PMID 37208522, 2023). "In breast cancer, researchers found that C5aR1-positive neutrophils secrete IL-1-β and TNF-α and they cooperatively activate ERK1/2 signal and phosphorylate WTAP at serine 341 to stabilize WTAP protein." (PMID 35251177, 2022). "In this study, we used Oncomine and The Cancer Genome Atlas (TCGA) databases to jointly analyze the expression of m6A “writer” in breast cancer including METTL3, METTL14, WTAP, RBM15, RBM15B, and ZC3H13, indicating that the mRNA expression levels of METTL14 and ZC3H13 were lower in tumor samples." (PMID 33363011, 2020). "In this study, we used a series of bioinformatic databases and tools to jointly analyze the expression of m6A methylation transferases (METTL3, METTL14, WTAP, RBM15, RBM15B and ZC3H13) and investigate the prognostic value of METTL14 and ZC3H13 in breast cancer." (PMID 33363011, 2020). "Strikingly, WTAP and the eraser FTO were downregulated in breast cancer cell lines compared to normal epithelial cells, whilst no changes were observed for ALKBH5." (PMID 36725888, 2023).